MDM4 (MDM4 regulator of p53)
Diseases named in the same sentence as MDM4 in open-access papers (continued):
Sharing a sentence is not in itself a finding about the gene and the disease.
cancer (continued). "In IOT, the LINC00324/miR-214-5p/CDK6|CCND1|MDM2|MDM4 axis promotes cancer cell proliferation and inhibits cancer cell apoptosis." (PMID 36620587, 2022). "In different cancers, it has been shown that MDM4 ubiquitination is inhibited by a ribosomal RNA, namely non-coding 5S rRNA, which binds to the RING-finger domain of MDM4." (PMID 34065345, 2021). "Overall, these data indicate that high MDM4 levels inhibit the EOC metastatic process contributing to restrain cancer progression and suggest that evaluation of its levels can be a useful marker for prognostic and therapeutic purposes in EOC." (PMID 34052831, 2021). "Regarding specific cancer-associated genes, the CYT-high subgroup had more CNAs, including gains in NF1, CDK12, ERBB2, RARA, MDM4 and MYC; and losses in BRCA1, CD274 and APC." (PMID 34316699, 2021). "Cancers that are characterized by overexpression of MDM4 are particularly likely to respond to such therapies." (PMID 33536467, 2021). "The overexpression of MDM4 has been observed in many different tumors, adding up to 2.9% of all cancers according to The Cancer Genome Atlas using cBioPortal, with higher frequencies observed of retinoblastoma and breast cancer as well as tumor cell lines." (PMID 34065345, 2021). "In contrast to MDM2, MDM4 is expressed at extremely low levels in adult tissues such as the eye, heart, and lung, but at higher levels in various types of cancer cells." (PMID 34144037, 2021). "Estrogen receptor-α is an important transcription factor of MDM4 and is frequently overexpressed in cancer." (PMID 34065345, 2021). "While skeletal α-actin gene, ACTA1, was recurrently amplified or overexpressed, its amplifications and deletions were co-regulated with MDM4 at chromosome 1q42.13 across cancers." (PMID 33217970, 2020).
cancer (continued). "Antisense oligonucleotides and specific inhibitors of ﻿Cdc-like kinases (CLKs) were shown to promote a switch in MDM4 alternative splicing in cancer cells." (PMID 32934219, 2020). "Based on the analyses of MDM4 gene amplification and overexpression on the mRNA level, the initial estimates of MDM4 overexpression in human cancers were around 17 %59." (PMID 32934219, 2020). "We show that CDK9 inhibition or knockdown can have a profound effect on the levels of MDM4 oncoprotein in cancer cells overexpressing MDM4 and human pluripotent stem cells, with a minimal impact on MDM2 expression." (PMID 32934219, 2020). "As in cancer cells, MDM4 expression was strongly inhibited by dinaciclib, roscovitine, flavopiridol, atuveciclib, and RO3306 in both lines, while MDM2 levels changed only minimally." (PMID 32934219, 2020). "In the current study, we link, for the first time, CDK activity to the overexpression of the MDM4 (MDMX) oncogene in cancer cells." (PMID 32934219, 2020). "It has been reported that MDM4 is highly expressed in various kinds of cancers and is regulated by miRNAs." (PMID 31824846, 2019). "MDM2 and MDM4 are often overexpressed in cancers and therefore serve as promising therapeutic targets." (PMID 30886745, 2019). "MDM4, MRTFA, and WASH5P were each highly up-regulated in embryos of poor morphology and are each in some way implicated in cancer." (PMID 31548358, 2019). "Dysregulation of MDM4 in cancer has drawn significant attention over the last two decades and now fascinating recent findings indicate that its influence extends well beyond this context." (PMID 30689920, 2019). "Increasing miR-1307 levels or reducing MDM4 levels each sensitize these resistant cancer cells to cisplatin." (PMID 30689920, 2019). "TP73 gene is rarely mutated in cancers and p73 protein is often inactivated by binding to oncogenic partners including MDM2, MDM4, ΔNp73, or mutant p5323." (PMID 30886745, 2019). "Pertinently, in tumor cells, nuclear location of MDM4 is reported to predominate, suggesting that its stabilized mislocation is a mode of its deregulation in human cancer." (PMID 30689920, 2019).
cancer (continued). "The MDM4 gene (also known as HDMX or MDMX) is located at chromosome 1q32, a region that is frequently found to be amplified in cancer." (PMID 27687591, 2016). "In line with this, the MDM4 gene has been found amplified and overexpressed in several cancer forms, and studies in transgenic mice have shown that overexpression of Mdm4 induced spontaneous tumor formation and accelerated tumorigenesis." (PMID 26867771, 2016). "Overexpression of MDM4 has also been reported in various cancers, and MDM4 inhibitors were recently developed along with dual inhibitors against MDM2 and MDM4." (PMID 27659536, 2016). "Similar to MDM2, spontaneous tumorigenesis was observed in mice overexpressing MDM4, and elevated expression of MDM4 or gene amplification has been described in a number of cancers." (PMID 27916892, 2016).
cancer (continued). "Owing to the prevalence of MDM4 genomic amplification/mRNA overexpression in human cancers, several strategies aimed at inhibiting the oncogenic activity of MDM4 have been explored." (PMID 26095524, 2015). "As an example, we detected differentially expressed transcript variants of the cancer genes NF1 and MDM4." (PMID 26109056, 2015). "In this study, 7,079 cancer cases and 3,747 healthy controls were analyzed for MDM4 SNP34091 status." (PMID 26471763, 2015). "Both MDM2 and MDM4 function as oncogenes and their deregulated expression has been reported in various types of human cancers, including soft tissue sarcoma, breast cancer, retinoblastoma, and melanoma." (PMID 25621298, 2014). "Recently, small molecular inhibitors of MDM2 and MDM4 have been developed and are currently being evaluated in clinical trials for several cancer types." (PMID 24874471, 2014). "Some cancer cells expressing high levels of MDM4 are reportedly resistant to small-molecule MDM2 inhibitors." (PMID 25621298, 2014). "miR-191 is reported to regulate cancer progression and chemosensitivity in ovarian cancer by modulating the level of MDM4 through binding with an illegitimate site (rs4245739) within the 3′ UTR." (PMID 24795757, 2014). "A deeper understanding of MDM4 biology may facilitate the development of novel targeted therapies for various cancers." (PMID 41976281, 2026).
cancer (continued). "Finally, we discuss the current landscape in the development of MDM2 and MDM4 inhibitors for cancer therapy." (PMID 39960347, 2025). "Our study is the first attempt to perform a pan-cancer analyses of MDM4, which confirms the importance of MDM4 in tumor diagnosis, helps to explore its mechanism in tumor development, and provides better options for successful implementation of targeted therapies." (PMID 38281029, 2024). "The role of MDM4 in cancer remains controversial in current literature." (PMID 39543140, 2024). "Finally, MDM4 has been shown to also be the driver of the addiction of cancers to chromosome 1q gains to support their malignant growth." (PMID 39572522, 2024). "Studies have shown diverse effects of MDM4 depending on context and cancer type." (PMID 39543140, 2024). "Through a TCGA pan-cancer analysis, the MDM4 mRNA expression levels were initially watched." (PMID 38281029, 2024). "MDM4 is significantly amplified (14% up to 43%) in several cancer types." (PMID 39273507, 2024). "It regulates the alternative splicing of cancer-related transcripts MDM4 and SLK in HCT116 cells." (PMID 36611187, 2023). "Both MDM2 and MDM4 proteins are overexpressed in a range of human cancers." (PMID 36624687, 2023).